MGMT (O-6-methylguanine-DNA methyltransferase)
Diseases named in the same sentence as MGMT in open-access papers (continued):
Sharing a sentence is not in itself a finding about the gene and the disease.
tumor (continued). "In the present study, we were able to detect methylation in cfDNA by both MSP-blood and PYR-plasma, but when we examined the capacity of MSP-blood and PYR-plasma to predict MGMT methylation status by the matched tumor assessments, concordance was relatively low, with a sensitivity of 30–40%." (PMID 31366977, 2019). "Finally, if the tumor presented low MGMT and high MPG expression, cytotoxicity or resistance would depend on several factors: an integral MMR pathway, the persistence of mismatch pairing, the tolerance of mutations, and the adequate repair of adducts by BER." (PMID 29963012, 2018). "Interestingly, we detected a significant increase in MGMT expression in the recurrent tumor from patient #1 compared to its matched primary tumor, whereas MGMT expression was not significantly altered in recurrent tumors from patients #2 and #3." (PMID 30054476, 2018). "Furthermore, to avoid the statistical bias for predictive value of MGMT gene parameters owing to tumor heterogeneity, a re-sampling analysis was done which substantiated for reproducibility of the results." (PMID 29712977, 2018). "However, tumor cells with O-6-methylguanine-DNA methyltransferase (MGMT) gene expression are capable of repairing the DNA damage induced by temozolomide." (PMID 29644003, 2018). "Still, this finding is in agreement with previous investigations of GBM patients, which name concomitant or adjuvant chemotherapy, particularly with temozolomide, as significantly improving survival outcomes in GBM patients, especially those whose tumor cells express MGMT." (PMID 30443448, 2018). "MGMT was also methylated in both the primary tumor and at recurrence." (PMID 29487696, 2018). "In tumor microenvironment MGMT, after its inactivation, may interact with transcription factors of different adaptive response genes, as it has been shown with ROS, which induce resistance to subsequent courses of TMZ." (PMID 29963012, 2018). "Inactivation of the gene of MGMT play an important role in tumor aberrant progression." (PMID 29362385, 2018). "We also determined whether MGMT promoter methylation had a correlation in relation to clinicopathological characteristics, including pathological types, clinical stage, and tumor grade." (PMID 29195029, 2018). "But as the malignant tumor tissue is generally in hypoxic state, and the MGMT inhibition effect of FM19G11 majorly relies on the hypoxia‐inducible factor‐1‐alpha pathway, we think FM19G11 probably preferentially inhibit MGMT activity in tumor than in the normal tissues." (PMID 29761922, 2018). "Pyrosequencing, an objective tool to evaluate the methylation status of the MGMT promoter which detects pyrophosphate release on nucleotide of the next complementary nucleotide, has emerged as a reliable and accurate alternative in other tumor types." (PMID 29344904, 2018). "The purpose of our study was to seek certain variables derived from conventional structural image features including multifocal, tumor cross midline, tumor location, enhancement, cyst, necrosis, edema, side, which may reflect MGMT promoter methylation status." (PMID 29467012, 2018). "Here we explored the mechanisms and pharmacological interactions associated with the combination of inhibition of the most studied DNA repair protein MGMT and EGFR, a receptor tyrosine kinase to which is associated aggressive tumour progression and reduced drug sensitivity." (PMID 30416678, 2018). "Young age, gross complete tumor resection, neuronavigation with 5 Ala, Gradel (BCNU waffle), irradiation, CCRT, IDH-1 mutation, methylated MGMT, TMZ, Avastin, and immunotherapy have all been studied and may improve the tumor control." (PMID 29910795, 2018).
tumor (continued). "During the early stage of carcinogenesis, epigenetic and genetic alterations are common events, and silencing of this MGMT gene by its promoter methylation is one of the major mechanism for carcinogenesis in tumor tissues of various cancers, including NSCLC10,12,46." (PMID 29362385, 2018). "In line with their results, MGMT only correlated with tumor grade and tumor type." (PMID 29851970, 2018). "On the contrary, some tumors may display increased MGMT activity when compared to their corresponding healthy tissue thereby presenting an increase in tumor resistance to TMZ treatment." (PMID 29963012, 2018). "In 2/48 (4%) cases the MGMT promoter changed to methylated (defining a cut-off for methylated MGMT promoter ≥ 8%) in one patient after 1 h and in another patient after 12 h after tumor removal." (PMID 29344904, 2018). "NEO412 at 75 and 150 mg/kg displayed clear anti-tumor effects in this MGMT-positive tumor model." (PMID 30651933, 2018). "However, tendencies were observed that patients with an ELMO1 hypermethylated tumor were unmethylated at the MGMT promoter (p = 0.053), and likewise that patients with an ELMO3 hypomethylated tumor were unmethylated at the MGMT promoter (p = 0.137)." (PMID 29495584, 2018). "Thirty-seven tumor samples were available for MGMT promoter methylation testing by pyrosequencing." (PMID 30301187, 2018). "Additionally, the same effect was also detectable when using a P-PRAS40 median split in the MGMT promoter unmethylated tumor cohort (p = 0.03, Wilcoxon)." (PMID 30129426, 2018). "In conclusion, in the case of A2058, we could establish proof-of-principle that TMZ treatment triggered the selection of MGMT-positive cells, which were derived from a pre-existing minority of cells that survived and eventually dominated the tumor mass." (PMID 30274152, 2018). "Moreover, these cells express also usually high levels of MGMT, and therefore they are involved in chemotherapy resistance and are responsible for tumor recurrence." (PMID 29558958, 2018). "Furthermore, promoter methylation of both CDKN2A (p14ARF) and MGMT has been associated with tumour stage and the addition of GSTP1 and TIMP3 promoter methylation allowed to discriminate invasive tumours." (PMID 30149597, 2018). "The methylation status of MGMT-promoter was determined in all tumours (n = 50) by MSP." (PMID 29515653, 2018). "The MGMT levels show wide variations across different tumor types or among tumors of the same type." (PMID 29712977, 2018). "As both, IDH1 mutation and MGMT expression, can predict outcome of therapy obtained in vitro results cannot directly be translated to the clinical situation of our tumor sample analysis." (PMID 29755294, 2018). "The MGMT methylation status may predict the response to alkylating agents, and may have more prognostic value than performance status or other tumor characteristics." (PMID 28730289, 2017). "In conclusion, the present meta-analysis indicates that MGMT expression is indeed associated with PA recurrence, but not with invasiveness, age, gender, tumor size or functional status." (PMID 28152515, 2017). "Consequently, GBM patients whose tumours express low MGMT level, due to promoter hypermethylation, are more responsive to TMZ based therapy." (PMID 28208677, 2017). "Only 2 patients had methylated MGMT tumors and 7 patients had prior gross total tumor resections." (PMID 29108308, 2017). "The methylation statuses of P16, RASSF1A, APC, RARβ, DAPK, CDH13, and MGMT were not linked to age, gender, smoking behavior, and tumor stage and histology in NSCLC." (PMID 28404957, 2017). "It is essential in killing bulk tumor and can be used even when MGMT expression is high." (PMID 28477008, 2017). "In-vitro studies showed that 5-FU depletes tumor levels of MGMT." (PMID 29262620, 2017).
tumor (continued). "Regarding protein loss (negative immunohistochemical staining results), ATRX loss in primary tumours was more common in A and AA than in pGBM, whereas MGMT loss was not significantly different among all tumour grades." (PMID 29026176, 2017). "As a result, TMZ monotherapy could be a treatment option for patients who have MGMT methylated tumor(s) with AA genotype and cannot receive radiotherapy." (PMID 29036186, 2017). "This study adds to the current knowledge base by including a large number of patients with a rare tumor, patients with higher grade tumors, patients treated previously with chemotherapy, everolimus and sunitinib, as well as the reporting of MGMT expression where tissue was available for analysis." (PMID 29262620, 2017). "Today, advanced technology allows for MGMT testing with smaller tumor tissue specimens; hence, this test may be integrated in future TGF-β-directed studies." (PMID 28481241, 2017). "Low-to-moderate MGMT immunoexpression was also found to significantly correlate with surgical invasiveness of the tumor at the initial operation and may therefore be used as a potential indicator of more aggressive biological behavior." (PMID 28900805, 2017). "The reason for not performing MGMT testing was based on the limited amount of tumor tissue and the focus on TGF-β-associated signaling and immune markers." (PMID 28481241, 2017). "However, due to intrinsic or acquired overexpression of the DNA alkyltransferase, O6-methylguanine-DNA methyltransferase (MGMT), in 60% of patients with HGGs, tumor cells are resistant to TMZ." (PMID 28556811, 2017). "While the somatic mutation prevalence in LGGs is higher, one explanation is that active MGMT in LGGs might repair DNA damage and further protect the tumor cells from apoptosis and cell death." (PMID 28575062, 2017). "Our major finding suggested that MGMT promoter hypermethylation had a significantly increased risk in tumor tissues (OR = 4.37, 95% CI: 2.68–7.13) compared with non-cancerous tissues and exfoliated cells." (PMID 28986566, 2017). "However, a DNA repair enzyme, O6-methylguanine DNA methyltransferase (MGMT), is able to reverse the anti-tumor effect of TMZ, and mainly contributes to the chemoresistance in a fraction of patients." (PMID 29225516, 2017). "It was hypothesized that tumor cells with methylation of MGMT are likely to remain in G2/M checkpoint, resulting in increased sensitivity to chemoradiation." (PMID 27643594, 2016). "We discovered an inverse relationship between miR-29c and Sp1/MGMT levels in tumor samples." (PMID 27384876, 2016). "MGMT methylation was detected in 17 of 64 (26.6%) patients, and was not correlated with sex, age, tumor differentiation, CIMP, MSI, or KRAS mutations." (PMID 27643594, 2016). "Patients with adequate tumor specimens were analyzed for genetic changes including isocitrate dehydrogenase 1 (IDH1) mutations, 1p/19q loss of heterozygosity (LOH) and promoter methylation of O6-methylguanine-DNA methyltransferase (MGMT)." (PMID 27590514, 2016). "The loss of the MGMT protein function is related to tumor spread to the lymph nodes and advanced stages of the disease." (PMID 26810771, 2016). "Whether these differences may be in part due to tumor-related factors such as IDH1/2 mutations and MGMT promoter methylation is unclear due to the small number of subjects." (PMID 26910903, 2016). "Moreover, we also evaluated the correlation between MGMT promoter methylation and gender, age status, tumor stage, tumor types and H. pylori status in cancer." (PMID 27824946, 2016). "The frequency of MGMT promoter methylation in tumor was 46.70% and 23.23% in control group." (PMID 27657735, 2016).
tumor (continued). "TMZ has demonstrated the ability to deplete the MGMT repair protein levels in tumor cells, resulting in improved efficacy of alkylating agents, which may contribute to the therapeutic synergy seen when combining this agent with Gliadel." (PMID 27557526, 2016). "The association between BM and mutation in PIK3CA and BRAF, expression of NCAM, EGFR, and CXCR4, MGMT methylation and increase in the tumor marker CA19.9 have also been investigated, but only in one or two studies each and on small samples, so the possible predictive potential is hard to determine." (PMID 27037031, 2016). "Next we tested whether probe NR-1 can be used to differentiate levels of MGMT activity in different tumor cell lysates." (PMID 27035132, 2016). "We selected MGMT for further study because of its recognized role in GBM tumor biology." (PMID 27595933, 2016). "In order to take into account clinical (age at 1st diagnosis, EOR at 1st surgery, TMZ at 1st diagnosis, therapies other than BCNU at tumor recurrence) and molecular (MGMT promoter methylation) prognostic factors as potential confounders, a multiple Cox proportional hazard analysis was performed." (PMID 26865253, 2016). "Therefore, we evaluated the possible associations between the frequency distributions of DAPK-1, MLH1, and MGMT methylation and the Lauren morphological tumor classification." (PMID 26810771, 2016). "For MGMT promoter methylation analysis, DNA from 330 tumor samples was investigated by MSP assay." (PMID 26556853, 2016). "High tumor MGMT expression in patient samples is associated with TMZ resistance since tumor cells lacking MGMT activity are significantly more sensitive to the cytotoxic effects of TMZ." (PMID 27277032, 2016). "A consecutive pathologic electron microscopy showed an atypical sparsely granulated corticotroph tumour, with an MIB-1 index >5%, very low activity of O6-methylguanine DNA methyltransferase (MGMT) in tumour cells, and positive receptor SSRT 2A (weak cytoplasmic) reaction." (PMID 26221547, 2015). "First, the number of specimens for evaluating promoter methylation was relatively small, which may fail to describe the complete picture of prolactinoma MGMT promoter methylation and its correlation with tumor and patient characteristics." (PMID 26400193, 2015). "Thus, only patients with an intended GTR and similar MGMT promotor state, eloquent location, recurrent surgery, tumor size and age were compared." (PMID 26115409, 2015). "The protective effect of MGMT activity in tumour tissue is connected with resistance to TMZ drug." (PMID 26309255, 2015). "However, therapeutic benefits of TMZ can be compromised by the expression of O6-methylguanine methyltransferase (MGMT) in tumor tissue." (PMID 26546412, 2015). "MGMT status was available for 14 patients; only 3 patients had promoter-methylated tumor." (PMID 25935109, 2015). "Serum albumin levels did not vary significantly with sex, age, tumor size, degree of resection, MGMT promoter methylation and IDH1-R132H mutation status." (PMID 25880463, 2015). "It is known that silencing of MGMT gene by the methylation of the cytosine (m5C) residue (but not m7G, m3A or O6mG) within the promoter region results in decrease of the enzyme expression in tumour cells." (PMID 26309255, 2015). "The data also suggest that BMP7 possesses the ability of anti-EMT/migration/invasion, induction of tumor stem cell differentiation/senescence, and down-regulation of MGMT and drug efflux transporters, thereby allowing for sensitization of GSC to low-dose TMZ treatment." (PMID 26546412, 2015). "This may be explained by the selection and outgrowth of tumor subclones with unmethylated MGMT promoter during TMZ treatment." (PMID 25720744, 2015). "To search for cellular regulators of MGMT as an alternative approach to inhibit expression of MGMT in tumour cells we used gene ontology analysis to test for aberrantly expressed genes or signal transduction cascades in cancers with elevated expression of MGMT." (PMID 26603103, 2015).
tumor (continued). "Moreover, pseudo-progression cannot be definitively excluded because the tumor is MGMT-methylated and disease progression was observed only 4 months after chemoradiation treatment." (PMID 26423602, 2015). "MGMT immunopositivity was <25 % in 106/136 tumor specimens (77.94 %)." (PMID 26400193, 2015). "Therefore, it is necessary to explore detection methods using sampling from multiple sites of the tumor to derive the MGMT gene promoter methylation status to study the corresponding sequential chemotherapy dosage and mode of administration." (PMID 25211033, 2014). "The DNA repair enzyme MGMT inhibits the killing of tumor cells by alkylating chemotherapy agents." (PMID 25198391, 2014). "The amount of MGMT in the tumor is therefore a key node in alkylating drug resistance." (PMID 25557167, 2014). "O6-methylguanine-DNA methyltransferase (MGMT) is a DNA repair enzyme, which is responsible for the resistance of cancer cells to several alkylating agents, thus conferring chemoresistance to certain tumor types." (PMID 23990015, 2014). "Tumour MGMT promoter methylation was seen in 73 (35%) of 209 patients tested." (PMID 24864257, 2014). "Our results support the hypothesis that MGMT expression may be an OS biomarker as useful as tumor stage or differentiation grade and that CD133 expression may be a predictive biomarker of DFS." (PMID 25015560, 2014). "Secondly, we have shown that although MGMT is expressed in the majority of MB patients’ tumours, and is able to directly repair the effects of DNA alkylating agents it cannot repair the effects of two novel imidazotetrazine derivatives of TMZ (N-3 sulfoxide and N-3 propargyl) in MB cells." (PMID 24887326, 2014). "In addition, childhood tumours with a methylated MGMT promoter have previously been shown to have a higher average survival than those without promoter methylation." (PMID 25026297, 2014). "However, it has been suggested that some factors increase the rate of distant recurrence only in certain subgroups, such as patients with methylated MGMT promoter, very extensive resections, and tumor involvement of the subventricular zone (SVZ)." (PMID 24135848, 2014). "MGMT expression was assessed in all tumours of origin for our cell lines by IHC." (PMID 24887326, 2014). "Among the 6 AOA tumours 5/6 had IDH1 mutations, and all 6 were judged to show methylation of MGMT Considering only tumours where we had results from both MGMT and IDH1/2 assays, among the AA 34/39 were judged to have methylation of MGMT and 31 of these 34 (91%) had IDH1 mutations." (PMID 24952577, 2014). "Overall, tumor stage 3, moderately differentiated tumors, presence of lymphatic invasion and absence of metastasis was more frequently observed in tumors with mutated Kras and/or methylated RASSF1A, FHIT and MGMT genes." (PMID 23573237, 2013). "PTEN and CDKN2A methylation levels were low and increased in late stage III and IV (p = 0.003, p = 0.004 between stage I and III, p = 0.018 and p = 0.003 between stage I and IV), while MGMT methylation levels were low and appear to decrease with tumor stage (p = 4.5e-4 between stage I and IV)." (PMID 24093668, 2013). "However, as GBMs with silenced MGMT cannot repair the DNA correctly, treatment with alkylating agents such as temozolomide has been demonstrated to be more effective in this group of tumours, making it a valuable biomarker for predicting drug responsiveness." (PMID 22771539, 2013). "Our findings further suggest cooperation between genetic and epigenetic events for effective MGMT silencing, which might be more predictive of tumor sensitization to alkylating agents, such as Temozolomide." (PMID 23505468, 2013). "Moreover, accumulation of normal cells in the tumor biases the assessment of MGMT expression in the tumor." (PMID 23873296, 2013). "MGMT is a DNA repair protein that protects GBM tumor cells from alkylating agents." (PMID 24086323, 2013). "By contrast, MGMT methylation is common in tumours amplified for PDGFRA alone." (PMID 23990986, 2013).